PARK7 (Parkinsonism associated deglycase)
Diseases named in the same sentence as PARK7 in open-access papers (continued):
Sharing a sentence is not in itself a finding about the gene and the disease.
asthenozoospermia (5 papers, 2018 to 2025). "In addition, PARK7 has been identified as a target of miR-4485-3, whose downregulation has also been associated to asthenozoospermia." (PMID 34639144, 2021). "Under oxidative stress conditions associated with asthenozoospermia, PARK7 has been observed to be translocated from the equatorial segment to the midpiece, which has been proposed as a possible protective mechanism for sperm to maintain their mitochondrial function." (PMID 34639144, 2021). "In effect, PARK7 has been found downregulated in patients with asthenozoospermia, varicocele, or oligozoospermia." (PMID 34639144, 2021). "In patients with asthenozoospermia, characterized by a reduction in sperm motility, the relative content of PARK7 is lower in both ejaculated sperm and seminal plasma." (PMID 34639144, 2021). "Furthermore, previous investigations have explored PARK7’s relevance to male fertility, revealing its downregulation in conditions like oligozoospermia, asthenozoospermia, and varicocele." (PMID 40563475, 2025). "In addition to men suffering from asthenozoospermia, PARK7 is downregulated in patients with varicocele and oligospermia, thus emphasizing its importance for male fertility." (PMID 34639144, 2021). "Recently, Park7 was observed as a target gene for the mitochondria-related miRNA miR-4485-3p which may link mitochondrial dysfunction and male asthenozoospermia." (PMID 34344298, 2021).
astrocytoma (5 papers, 2013 to 2025). "PARK7 is highly expressed in 92.8% of patients with astrocytoma, and this is directly correlated with the aggressiveness of the disease and the poor survival of patients with astrocytoma." (PMID 32357493, 2020).
cognitive decline (5 papers, 2017 to 2025). "Individual carrying PARK7 pathogenic variant typically experience disease onset at an average age of 27 years and often exhibit prominent NMS, including mental health disorders and cognitive decline." (PMID 38020640, 2023).
Hepatic steatosis (5 papers, 2017 to 2022). Steatosis is a term used to denote lipid accumulation within hepatocytes. "In contrast to the reduced diet‐induced hepatic steatosis in Park7−/− mice, we found that Park7 deficiency increased TRAS, suggesting that the underlying mechanisms of diet‐induced hepatic steatosis and TRAS are different." (PMID 36149763, 2022). "This is consistent with a previous finding showing that hepatic PTEN overexpression ameliorated the development of hepatic steatosis in liver‐specific HuR knockout mice, given that Park7 is a negative regulator of PTEN." (PMID 36149763, 2022). "We previously found that Park7−/− mice were resistant to HFD‐related hepatic steatosis by expediting free fatty acid (FFA) utilization." (PMID 36149763, 2022). "The deletion of PARK7 could promote fatty acid oxidation and prevent hepatic steatosis in mice." (PMID 34749647, 2021).
Infertility (5 papers, 2018 to 2025). "There is inadequacy in sperm motility in humans and other species, and infertility was also observed due to the PARK7 mutations." (PMID 35207708, 2022). "Acetylation changes in PARK7 may weaken its antioxidant and cytoprotective roles, increasing sperm vulnerability to oxidative injury and linking infertility with other redox-associated diseases." (PMID 41462610, 2025). "IPA analysis identified that the oxidation of protein pathway was inhibited due to overexpression of HSPA4 (4.08 folds), ALDH1A1 (10.32 folds) and PARK7 (2.69 folds) proteins in the post-antioxidant treatment group of idiopathic infertile men." (PMID 31623114, 2019).
uveal melanoma (5 papers, 2009 to 2025). A melanoma derived from melanocytes of the uveal tract. "show that PARK7-silenced uveal melanoma cells exhibit abnormalities in the PI3K/Akt pathway." (PMID 40860809, 2025).
frontotemporal dementia (4 papers, 2021 to 2025). Frontotemporal dementia (FTD) comprises a group of neurodegenerative disorders, characterized by progressive changes in behavior, executive dysfunction and language impairment, as a result of degeneration of the medial prefrontal and frontoinsular cortices. "GRN, one of the causative genes of frontotemporal dementia, is known to be regulated downstream of PARK7 in the context of neuroprotection." (PMID 35910227, 2022).
leukemia (4 papers, 2011 to 2022). A malignant (clonal) hematologic disorder, involving hematopoietic stem cells and characterized by the presence of primitive or atypical myeloid or lymphoid cells in the bone marrow and the blood. "PARK7 KO in leukemia cells reduces proliferation and induces apoptosis via regulation of the cell cycle and apoptosis-related proteins, including Cdk2, cyclin D1, c-Myc, NF-κB, Bcl-2, and PTEN." (PMID 32357493, 2020). "PARK7 is highly expressed in patients with acute leukemia (AL) and leukemia cell lines, compared to that of healthy patients and cells of healthy donors, respectively." (PMID 32357493, 2020). "Diallyl disulfide (DADS) has anti-cancer potential, and treatment with DADS induces apoptosis and inhibits the metastatic potential of leukemia cells by suppressing the expression of oncoproteins, including PARK7." (PMID 32357493, 2020).
liver cancer (4 papers, 2017 to 2024). An epithelial or non-epithelial malignant neoplasm that arises from the liver. "Subsequently, we conducted CO-IP experiments, which confirmed that EFCAB7 directly binds to PARK7 in liver cancer cells, consistent with the mass spectrometry results." (PMID 39276379, 2024).
ulcerative colitis (4 papers, 2020 to 2023). An inflammatory bowel disease involving the mucosal surface of the large intestine and rectum. "Previously, our research group reported elevated expression of PARK7 in the duodenal mucosa of therapy-naive children with CD, and genome-wide association studies identified PARK7 polymorphisms as a predisposing factor in CD and ulcerative colitis." (PMID 32963695, 2020). "After integrating the multi-omics data between mQTL-eQTL and eQTL-pQTL, we identified two mitochondrial genes, i.e., PARK7 and ACADM, with tier 1 evidence for their associations with IBD and ulcerative colitis (UC)." (PMID 38103512, 2023).
varicocele (4 papers, 2015 to 2025). A condition characterized by the dilated tortuous veins of the spermatic cord with a marked left-sided predominance. "Overexpression of PARK7 seen in unilateral varicocele patients may be a mechanism to control and protect against oxidative stress effects." (PMID 25890347, 2015). "We found that PARK7 was overexpressed with low abundance in the unilateral varicocele group." (PMID 25890347, 2015).
cervical cancer (3 papers, 2020 to 2024). A primary or metastatic malignant neoplasm involving the cervix. "The levels of PARK7 are significantly increased in patients with clear cell renal cell carcinoma and cervical cancer." (PMID 32357493, 2020). "The expression of IL24 by Ad- IL24 induces the apoptosis of cervical cancer cells by regulating the expression of proteins related to apoptosis, including PARK7." (PMID 32357493, 2020). "In addition, our previous studies showed that the anti-colorectal and cervical cancer effects of CPX are achieved through the induction of apoptosis and the inhibition of cell proliferation by downregulating PARK7 and ROS accumulation." (PMID 36678610, 2023).
COVID-19 (3 papers, 2021 to 2024). A disease caused by infection with severe acute respiratory syndrome coronavirus 2. "The decreased PARK7 in COVID-19 patients could also be connected to a metabolic imbalance." (PMID 38760690, 2024). "PARK7 is decreased in our COVID-19 patients and may not effectively perform its protective role against neurotoxicity and neuronal viability." (PMID 38760690, 2024).
Crohn disease (3 papers, 2021 to 2023). A gastrointestinal disorder characterized by chronic inflammation involving all layers of the intestinal wall, noncaseating granulomas affecting the intestinal wall and regional lymph nodes, and transmural fibrosis. "PARK7 expression was higher in the mucosa of children with Crohn’s disease compared to that of controls." (PMID 34272410, 2021).
laryngeal carcinoma (3 papers, 2011 to 2025). Carcinoma that arises from the laryngeal epithelium. "The loss of PARK7 expression in laryngeal cancer cells reduces their ability to form tumors in vivo and in vitro by increasing the expression of PTEN and suppressing the activation of AKT." (PMID 32357493, 2020). "PARK7 induces the expression of survivin, which inhibits the apoptotic proteins and induces the proliferation of laryngeal carcinoma cells." (PMID 32357493, 2020).
liver diseases (3 papers, 2021 to 2022). "We and other groups have showed that Park7 is associated with the pathogenesis of many liver diseases, mainly dependent on its redox function." (PMID 36149763, 2022). "Parkinsonism‐associated deglycase (Park7)/Dj1 is an important regulator involved in various liver diseases." (PMID 36149763, 2022). "Many researchers, including us, have shown that Park7 is involved in the process of many liver diseases." (PMID 36149763, 2022). "We and other groups have shown that PARK7 is involved in the pathogenesis of several liver diseases based on its redox function." (PMID 36149763, 2022).
medulloblastoma (3 papers, 2014 to 2025). A malignant, invasive embryonal neoplasm arising from the cerebellum. "The expression of PARK7 is markedly correlated with the increased expression of p-protein kinase B (AKT) and Ki67 and reduces the survival of patients with medulloblastoma." (PMID 32357493, 2020).
prostate tumors (3 papers, 2023 to 2024). "PARK7, or DJ-1, is a protein that regulates the oxidative stress response and is upregulated in prostate tumors." (PMID 37511304, 2023).
urothelial carcinoma (3 papers, 2022 to 2025). A malignant neoplasm derived from the transitional epithelium of the urinary tract (urinary bladder, ureter, urethra, or renal pelvis). "A biomarker panel comprising Stathmin-1, DJ-1/PARK7, Gamma-synuclein, and APOA4 reliably distinguished urothelial carcinoma from benign urothelium." (PMID 41357584, 2025).
acute myeloid leukemia (2 papers, 2023 to 2024). Acute myeloid leukemia (AML) is a group of neoplasms arising from precursor cells committed to the myeloid cell-line differentiation. "PARK7, in contrast, was upregulated in four cancer types, including SKCM when compared to normal tissues, and was downregulated only in acute myeloid leukemia (LAML)." (PMID 38189631, 2024).
allergic disease (2 papers, 2020 to 2024). An immune response that occurs following re-exposure to an innocuous antigen, and that requires the presence of existing antibodies against that antigen. "Specifically, we observed associations of genetic instruments for TLR1 and PARK7 with certain allergic diseases such as allergic asthma, allergic rhinitis, and eczema." (PMID 38887235, 2024).
brain cancer (2 papers, 2020 to 2024). A primary or metastatic malignant neoplasm affecting the brain. "PARK7 is a gene that supports cell survival, and its upregulation has been shown to be related to aggressive brain cancer progression." (PMID 38966281, 2024).
brain tumors (2 papers, 2020 to 2025). "Apart from being involved in brain tumors, the involvement of PARK7 in other types of human cancers has also been identified." (PMID 32357493, 2020).
celiac disease (2 papers, 2020 to 2022). An autoimmune genetic disorder with an unknown pattern of inheritance that primarily affects the digestive tract. "In this study, our research group demonstrated the increased mRNA expression and protein level of PARK7/DJ-1 in the small intestinal mucosa of patients with untreated coeliac disease." (PMID 35743072, 2022). "Our and other studies have demonstrated that intestinal expression of PARK7/DJ-1 is altered in the mucosa of patients with celiac disease or IBD." (PMID 35743072, 2022). "In this study, Comp-23, a PARK7/DJ-1 binding compound that protects PARK7/DJ-1 from overoxidation, was used to investigate the functional role of PARK7/DJ-1 in the pathomechanism of celiac disease." (PMID 35743072, 2022). "Moreover, we found that, following the introduction of a gluten-free diet, the amount of PARK7/DJ-1 normalizes, suggesting the possible role of PARK7/DJ-1 in the pathomechanism of celiac disease." (PMID 35743072, 2022). "In this study, we found that PARK7/DJ-1 immunopositivity is present in the epithelial cells of the duodenal crypt, and also in the lamina propria of duodenal biopsies derived from therapy-naive children with celiac disease." (PMID 35743072, 2022).
Cerebellar atrophy (2 papers, 2021 to 2024). Cerebellar atrophy is defined as a cerebellum with initially normal structures, in a posterior fossa with normal size, which displays enlarged fissures (interfolial spaces) in comparison to the foliae secondary to loss of tissue. "Similarly, most previously reported patients with biallelic PARK7 variants reported have shown no abnormalities, although a few cases showed cortical or cerebellar atrophy, suggesting that PARK7 variants do not substantially affect brain atrophy." (PMID 39170205, 2024).
clear cell renal cell carcinoma (2 papers, 2020 to 2022). "It has been identified that PARK7 is related to cisplatin resistance in NSCLC, small cell lung cancer (SCLC), and clear cell renal cell carcinoma." (PMID 32357493, 2020).
colon adenocarcinoma (2 papers, 2021 to 2022). "Our very recent results showed that inflammatory mediators of IBD, including LPS, TNF-α, and TGF-β, decreased the expression of PARK7/DJ-1 in HT-29 colonic adenocarcinoma cells." (PMID 35743072, 2022).
endothelial dysfunction (2 papers, 2023 to 2025). In vascular diseases, endothelial dysfunction is a systemic pathological state of the endothelium (the inner lining of blood vessels) and can be broadly defined as an imbalance between vasodilating and vasoconstricting substances produced by (or acting on) the endothelium. "Our findings reveal that endothelial dysfunction in ALI is mechanistically linked to desaturase‐mediated lipid metabolic perturbations, ferroptotic cell death, and lactate‐dependent histone modifications, with PARK7 serving as a pivotal node integrating these pathways." (PMID 41028978, 2025).
metastatic cancer (2 papers, 2021 to 2024). A carcinoma which has spread from the original site of growth to another anatomic site. "Importantly, increased bloodstream levels of PARK7 occur almost exclusively in metastatic cancer patients." (PMID 34771736, 2021).
muscle atrophy (2 papers, 2024 to 2026). The loss of muscle tissue due to inactivity or disease. "A range of complications are often reported in patients with PARK7 variants, including dysphagia, dysarthria, peripheral neuropathy, pyramidal tract disorders, dysphonia, and muscle atrophy; however, it may be that the type of complications that develop depend on the variant of each patient [15,]." (PMID 39170205, 2024).
osteoporosis (2 papers, 2017 to 2022). A condition of reduced bone mass, with decreased cortical thickness and a decrease in the number and size of the trabeculae of cancellous bone (but normal chemical composition), resulting in increased fracture incidence. "According to a previous study, the PARK7/DJ-1 protein level was increased up to 3 times in MLO-Y4 osteocytic cells, which were treated with N-BPs (nitrogen-containing bisphosphonates), a kind of osteoporosis drug." (PMID 35659283, 2022).
ovarian tumors (2 papers, 2020 to 2023). "PARK7 is upregulated in 81% of primary ovarian tumors and 80% of solid metastases." (PMID 32357493, 2020).
prion disease (2 papers, 2021 to 2023). A transmissible disease that is caused by a protein that is able to induce abnormal folding of normal cellular proteins, leading to characteristic spongiform brain changes, which are associated with neuronal loss without an inflammatory response. "Whereas the predominant pathogenic mutations in both SNCA and LRRK2 result in autosomal dominant pattern similarly to inherited forms of human prion diseases, other mutations (e.g., PARK2, PARK7, and PARK6) that involve PRKN, DJ-1, and PINK1 genes result in autosomal recessive patterns." (PMID 34360787, 2021).
thyroid cancer (2 papers, 2020 to 2021). "Several studies have reported the association between the expression of PARK7 and thyroid cancer." (PMID 32357493, 2020). "The expression of PARK7 is significantly increased in thyroid cancer cells and patients with thyroid cancer." (PMID 32357493, 2020). "The expression of PARK7 in thyroid cancer cells leads to the inhibition of apoptosis via suppression of the TNFSF10-induced generation of intracellular ROS." (PMID 32357493, 2020). "PARK7 is significantly upregulated in 94.6% of patients with thyroid cancer." (PMID 32357493, 2020). "PARK7 is highly expressed in patients with malignant thyroid cancer, indicating that PARK7 may be involved in thyroid cancer." (PMID 32357493, 2020).
Ureteral obstruction (2 papers, 2021 to 2022). Obstruction of the flow of urine through the ureter. "We first evaluated the levels of PARK7 during renal TIF in a mouse model of unilateral ureteral obstruction (UUO)." (PMID 34093596, 2021).
delirium (1 paper, 2023). A disorder characterized by confusion; inattentiveness; disorientation; illusions; hallucinations; agitation; and in some instances autonomic nervous system overactivity. "We found that PARK7 is increased in patients that will develop delirium, and mutations in the PARK7 gene are directly involved in early-onset PD." (PMID 37759795, 2023). "An increase in PARK7 in the CSF of patients that will develop delirium suggests inappropriate levels of oxidation may be present." (PMID 37759795, 2023).
mastitis (1 paper, 2020). Inflammation of breast tissue during lactation or postpartum due to an obstructed duct or infection. "Among the highly connected genes in the magenta module, GCLM, PARK7, SIL1, PHB, and CD68 were potentially associated with mastitis or similar biological processes, based on the previous studies." (PMID 32754201, 2020).
metachromatic leukodystrophy (1 paper, 2022). A rare lysosomal storage disorder characterized by intralysosomal accumulation of sulfatides in various tissues, leading to progressive deterioration of motor and neurocognitive function. "In four patients, rare heterozygous RDVs were detected in other neurodegeneration-associated genes, such as PRKN (PD), LRRK2 (PD), PARK7 (PD), C19ORF12 (NBIA), SPG11 (Spastic paraplegia-SP/ALS), and PSAP (Metachromatic leukodystrophy-MLD)." (PMID 35752680, 2022).
motor neuron degeneration (1 paper, 2024). "Together, these findings suggest that PARK7 variants might also be associated with motor neuron degeneration." (PMID 39170205, 2024).
neuronal ceroid lipofuscinosis type 7 (1 paper, 2022). "A homozygous deletion of exon 2 of the MFSD8 gene is associated with neuronal ceroid lipofuscinosis type 7 and a homozygous deletion of 16 exons in PARK7 was detected in a child with pathogenic SACS mutations." (PMID 34791078, 2022).
oesophageal cancers (1 paper, 2017). "It has been reported that in patients with lung, ovarian and oesophageal cancers, high expression of PARK7 predicts a poor outcome." (PMID 28686225, 2017).
oligodendroglioma (1 paper, 2018). A well-differentiated (WHO grade II), diffusely infiltrating neuroglial tumor, typically located in the cerebral hemispheres. "Many of these candidates (e.g. ELTD1, SDHB, SEPW1, SLC17A7, SZRD1, THAP3, ZBTB17) are likely to push, whereas others (e.g. CAP1, HBXIP, KLK6, PARK7, PTAFR) might counteract oligodendroglioma development." (PMID 29890994, 2018). "Interestingly, several of these genes (e.g. ELTD1, SDHB, SEPW1, SLC17A7, SZRD1, THAP3, ZBTB17) are likely to push, whereas other genes (e.g. CAP1, HBXIP, KLK6, PARK7, PTAFR) might restrict oligodendroglioma development." (PMID 29890994, 2018).